NLRP1 (NLR family pyrin domain containing 1)
Diseases named in the same sentence as NLRP1 in open-access papers (continued):
Sharing a sentence is not in itself a finding about the gene and the disease.
hepatic disease (1 paper, 2019). "Expression analysis for various inflammasomes in animal model suggested that NLRP1, NLRP3, and AIM2 were highly expressed in Kupffer cells and liver sinusoidal endothelial cells, while virtually absent in primary cultured hepatocytes in inflammatory and hepatic disease conditions." (PMID 31551961, 2019).
Hepatic steatosis (1 paper, 2025). Steatosis is a term used to denote lipid accumulation within hepatocytes. "IL-18 is induced upon NLRP1 activation and decreased upon NLRP1 loss, and its production could prevent hepatic steatosis." (PMID 40243151, 2025).
influenza infection (1 paper, 2025). "Multiple inflammasomes can be involved in IL-1β activation, including NLRP3, NLRP1, NLRC4, AIM2, IFI16 and RIG-I, however because GC B cells are not directly infected by influenza infection, we examined NLRP3 and AIM2 as they are activated by stimuli likely to be present in GC B cells." (PMID 40825032, 2025).
itch (1 paper, 2020). "All these results indicate that NLRP1 inflammasome-mediated inflammatory processes contribute to AEW-induced chronic itch." (PMID 32312281, 2020). "All these data suggest that NLRP1 inflammasome-mediated inflammatory signal is involved in chronic itch with gender differences." (PMID 32312281, 2020). "Therefore, our results indicate that NLRP1-dependent inflammation in the skin should be a triggering factor in AEW-induced chronic itch model, and that in the spinal cord is critical for the modulation of itch." (PMID 32312281, 2020). "Therefore, in this study, we mainly investigated the involvement of NLRP1 inflammasome in dry skin itch and explored whether NLRP1 inflammasome is related to age and gender differences in the chronic itch model." (PMID 32312281, 2020).
keratinization disease (1 paper, 2023). "Furthermore, a novel term for NLRP1-associated autoinflammatory disease with epithelial dyskeratosis (NADED) describing the spectrum of autoinflammatory keratinization diseases secondary to NLRP1 mutations is proposed." (PMID 38103162, 2023).
liver fibrosis (1 paper, 2022). "As the NLRP1 inflammasome is less well-studied, the role of the NLRP1 inflammasome in chronic liver disease and liver fibrosis remains unclear." (PMID 35707547, 2022).
macrophage activation syndrome (1 paper, 2022). A complication of rheumatic disease that is caused by excessive activation and uncontrolled proliferation of T lymphocytes and well-differentiated macrophages. "For instance, NLRP1 mutations lead to NLRP1-associated Auto-Inflammation with Arthritis and Dyskeratosis (NAIAD) and NLRC4 gain-of-function mutations triggers Syndrome of enterocolitis and Autoinflammation associated with mutation in NLRC4 (SCAN4) or recurrent Macrophage Activation Syndrome (MAS)." (PMID 35563744, 2022).
memory impairment (1 paper, 2023). "The results indicated that NLRP1-siRNA treatment significantly alleviates the learning and memory impairments in APP/PS1 mice." (PMID 37055801, 2023).
microcephaly (1 paper, 2021). A congenital or acquired developmental disorder in which the circumference of the head is smaller than normal for the person's age and sex. "Presence of NLRP1, NLRP3, and AIM2 together with elevated IL-1β, IL-18, and IL-33 could be detected in the brain of ZIKV-infected patients with microcephaly." (PMID 33796483, 2021).
neutropenia (1 paper, 2023). A decrease in the number of neutrophils found in the blood. "Furthermore, the neutropenia of larvae induced by forced expression of zebrafish flii was rescued by human wild type and S107D NLRP1." (PMID 37675820, 2023).
osteoarthritis (1 paper, 2024). A noninflammatory degenerative joint disease occurring chiefly in older persons, characterized by degeneration of the articular cartilage, hypertrophy of bone at the margins and changes in the synovial membrane. "Furthermore, high levels of pyroptosis-related cytokines (IL-1β, IL-18), produced by fibroblast-like synovial cells, have been found in the synovial fluid of patients with osteoarthritis, together with an increased expression of NLRP1 and NLRP3 inflammasomes." (PMID 39000412, 2024).
partial seizures (1 paper, 2017). "Therefore, the aim of this present study was to investigate the role of NLRP1 (rs8079034, rs878329), NLRP3 (rs4612666, rs10754558, and rs2027432), and P2X7R (rs3751143, rs208294) gene polymorphisms in Chinese partial seizures population." (PMID 28503575, 2017).
peripheral nerve injury (1 paper, 2015). Injury to a peripheral nerve. "It seems that especially monocytes contribute to the observed induction of NAIP1, NAIP2, and Nlrp1 at day 1 after peripheral nerve injury, while resident macrophages induce the expression of NAIP1, Nlrp3, ASC, and MCP-1 1 day after injury." (PMID 26253422, 2015).
Peritoneal Fibrosis (1 paper, 2019). Disorder characterized by a wide range of structural changes in PERITONEUM, resulting from fibrogenic or inflammatory processes. "First, although we showed that NLRP3 deficiency significantly attenuates MGO-induced peritoneal fibrosis, we have not examined whether deficiency of other inflammasome-forming PRRs, such as NLRP1, NLRC4, and AIM2, could inhibit peritoneal fibrosis." (PMID 31316105, 2019). "In this regard, we observed no significant changes of these molecules in mice after MGO treatment; therefore, we assume that NLRP1, NLRC4, and AIM2 inflammasomes are less likely to be involved in MGO-induced peritoneal fibrosis." (PMID 31316105, 2019).
peritonitis (1 paper, 2018). Inflammation of the peritoneum (tissue that lines the abdominal wall and covers most of the organs in the abdomen). "CLANmCas9/gNLRP3 was unable to entirely prevent septic shock and peritonitis likely because of the activation of other inflammasomes, such as NLRP1, NLRC4, and AIM23,5,7, and the inactivation of the NLRP3 inflammasome was insufficient to inhibit acute inflammation." (PMID 30291237, 2018).
pneumonia (1 paper, 2020). An acute, acute and chronic, or chronic inflammation focally or diffusely affecting the lung parenchyma, caused by an infection in one or both of the lungs (by bacteria, viruses, fungi, or mycoplasma.). "For example, NLRP1 (NLR Family Pyrin Domain Containing 1) enhances the host's resistance to pneumonia via detecting their virulence factors [Bacillus anthracis lethal factor (LF) protease]." (PMID 32849610, 2020).
retinal diseases (1 paper, 2020). "Whilst the present study suggests that NLRP3 is instrumental in DR-mediated RPE damage, more studies are required to fully elucidate NLRP1 inflammasome involvement in retinal diseases." (PMID 33396676, 2020).
schizophrenia (1 paper, 2024). A major psychotic disorder characterized by abnormalities in the perception or expression of reality. "Compared to controls, we quantified a significantly higher number of NLRP1-positive pyramidal neurons in the schizophrenia brains (p < 0.01), suggesting NLRP1 inflammasome activation in schizophrenia subjects." (PMID 38540722, 2024). "In the medial orbitofrontal cortex (Brodmann’s area 11/12) and dorsolateral prefrontal cortex (area 46) from both hemispheres of six schizophrenia subjects, the NLRP1 mRNA expression was significantly higher than in six control brains (p < 0.05)." (PMID 38540722, 2024). "In the context of major developmental hypotheses of schizophrenia, notably those concerning maternal immune activation and neuroinflammation, we studied NLRP1 expression and content in the postmortem brain tissue of 10 schizophrenia and 10 control subjects." (PMID 38540722, 2024). "We propose NLRP1 inflammasome as a potential biomarker and therapeutic target in schizophrenia." (PMID 38540722, 2024). "As the expression difference was highest for the medial orbitofrontal cortex in the right hemisphere, we assessed NLRP1-immunoreactive pyramidal neurons in layers III, V, and VI in the medial orbitofrontal cortex in the right hemisphere of seven schizophrenia and five control brains." (PMID 38540722, 2024).
spinal cord injury (1 paper, 2016). Penetrating and non-penetrating injuries to the spinal cord resulting from traumatic external forces (e.g., WOUNDS, GUNSHOT; WHIPLASH INJURIES; etc.). "NLRP1 inflammasomes were assembled and activated in neurons after spinal cord injury (SCI)." (PMID 26925775, 2016).
streptococcal infection (1 paper, 2019). Any of the several infectious disorders caused by members of streptococcus, a genus of gram positive bacteria belonging to the family Streptococcaceae. "Although NLRP3 and AIM2 participate in IL-1β release by bmDCs and MΦ following infection by GBS and S. pneumoniae, the implication of NLRP1 and NLRC4 have not yet been described following streptococcal infection." (PMID 31262357, 2019).
tendinitis (1 paper, 2024). Inflammation of a tendon, usually resulting from an overuse injury. "Our analysis revealed a distinct expression profile of inflammasome-related genes in tendinitis, with NLRP6, NLRP1, and MEFV showing significant correlations with immune checkpoint molecules." (PMID 38919626, 2024).
triple-negative breast carcinoma (1 paper, 2024). An invasive breast carcinoma which is negative for expression of estrogen receptor (ER), progesterone receptor (PR), and human epidermal growth factor receptor 2 (HER2). "The significant upregulation of NLRP1 protein levels in MDA-MB-231 cells suggests that the NLRP1 inflammasome pathway may be a potential therapeutic target for triple-negative breast cancer." (PMID 38990306, 2024). "Therefore, further research is required to explore the NLRP1 expression in MDA-MB-231 cells and its role in the pathogenesis and treatment of triple-negative breast cancer." (PMID 38990306, 2024).
uveal melanoma (1 paper, 2025). A melanoma derived from melanocytes of the uveal tract. "Conversely, NLRP1 upregulation was associated with poor OS in Uveal Melanoma (UVM) (p = 0.041, HR = 2.38) and KIRC (p = 0.035, HR = 1.37)." (PMID 40237399, 2025).
tumor (89 papers, 2012 to 2026). "A total of 303 mutations were identified in the NLRP1 gene across TCGA tumor subjects, comprising 243 missenses, 44 truncating mutations, 15 splice site alterations, and 1 in‐frame mutation." (PMID 40237399, 2025). "Abnormal expression of NLRP1 was associated with decreased sensitivity to multiple anti‐tumor drugs and small compounds." (PMID 40237399, 2025). "The paper investigates the expression pattern of NLRP1 and its associated survival prognosis across multiple tumor types using data from TCGA and several cancer‐associated databases." (PMID 40237399, 2025). "Since this study analyses the effect of NLRP1 mutations in pan‐cancers, the prognosis effect on a single tumour still needs further study." (PMID 39318060, 2024). "Overall, the GSEA analysis suggested that high NLRP1 expression is positively associated with immune‐related pathways in tumours, while negatively linked to metastasis‐related pathways." (PMID 39318060, 2024). "Inflammations have been linked to tumours, suggesting a potential association between NLRP1 and cancer." (PMID 39318060, 2024). "The fact that patients with germline gain-of-function mutations of NLRP1 are predisposed to develop cSCCs proves that the NLRP1 inflammasome represents a tumor promoter pathway in the development of NMSC." (PMID 36293159, 2022). "NLRP1 is a tumor promoter, as patients with gain-of-function mutations of NLRP1 suffer from inflammatory skin syndromes and have a predisposition for cutaneous SCCs." (PMID 36581625, 2022). "The low expression of NLRP1 is associated with poor prognosis and a low level of tumor immune cell infiltration in patients with LUAD." (PMID 36186792, 2022). "Moreover, SKCM, ACC, and UCS tumor subjects exhibited the highest frequencies of NLRP1 mutations (13.96%), deep deletions (2.2%), and amplifications (3.51%), respectively." (PMID 40237399, 2025). "The correlation analysis of immune cell infiltration showed that CASP1, NLRP3, and AIM2, which showed that pyroptosis was involved in the infiltration of immune cells in the tumor microenvironment and NLRP1 exhibited high diagnostic efficacy, while PYCARD demonstrated poor diagnostic efficacy." (PMID 40026444, 2025). "Taking together, NLRP1 mutations can act as a predictor of tumour prognosis." (PMID 39318060, 2024). "Since the expression of NLRP1 is positively correlated with the infiltration of tumor immune cells, this may provide clues into its underlying mechanism." (PMID 36277882, 2022). "Moreover, the level of NLRP1 expression was positively linked to the degree of infiltration of various TIICs (tumor-infiltrating immune cells)." (PMID 33658393, 2021). "Since NLRP1 is associated with immune infiltrating cells and immune pathway genes, further studies were conducted to determine whether it is related to common immune subtypes of tumours." (PMID 39318060, 2024). "We reveal that the NLRP1 mutation may be related to a good prognosis for the tumours." (PMID 39318060, 2024). "In the context of tumour regression and progression, low expression of the NLRP1 inflammasome indicated an increase in metastasis and recurrence in patients with NMSC." (PMID 42222687, 2026). "The common tumor types with significantly downregulated or upregulated NLRP1 expression patterns were identified between TIMER2.0, starBase, GEPIA2, and UALCAN databases." (PMID 40237399, 2025). "Our comprehensive analysis has revealed a consistent downregulation of NLRP1 across multiple cancer types, suggesting a potential role for NLRP1 as a tumor suppressor." (PMID 40237399, 2025). "Aberrant and chronic activation of NLRP1 predisposes patients for the development of cSCCs demonstrating that NLRP1 is a tumor promoter." (PMID 40593496, 2025). "It is also possible that suppression of NLRP1 expression in cSCCs protects the cancer cells from anti-tumor immunity induced by NLRP1 activation." (PMID 40593496, 2025).
tumor (continued). "Consistent with previous studies, our findings highlight the tumor‐suppressive influence of NLRP1 in the majority of TCGA cancer types." (PMID 40237399, 2025). "The results showed elevated levels of AIM2 in tumor tissues, while CASP1, NLRP3, and NLRP1 exhibited low expression in these tumor tissues." (PMID 40026444, 2025). "Kaplan–Meier plotter analysis was conducted to investigate the effect of differential NLRP1 expression on tumour prognosis." (PMID 39318060, 2024). "Through extensive big data analysis, we delved into the role of NLRP1 across various tumour types, constructing a comprehensive role map of its involvement in pan‐cancer scenarios." (PMID 39318060, 2024). "The down‐regulated NLRP1 decreases the tumour metabolic activity in LUAD, demonstrating the potential relationship between NLRP1 and tumour metabolism." (PMID 39318060, 2024). "NLRP1 is also significantly associated with most immune‐stimulating genes except for CD276, HHLA2, NTSE, PVR, TNFSF18 and UNBP1 in the HNSC‐excluded tumours." (PMID 39318060, 2024). "This study sheds light on the multifaceted role of NLRP1 in cancer, revealing its impact on expression, prognosis, immunity, metabolism and stemness across various tumour types." (PMID 39318060, 2024). "Collectively, NLRP1 emerges as a potential biomarker, as it exhibits significant correlations with the prognosis of various types of tumours." (PMID 39318060, 2024). "In more detail, NLRP1 is positively related to most MHC genes with statistical significance in pan‐tumours except for CESC, ESCA, HNSC, PCPG and THCA." (PMID 39318060, 2024). "We revealed that NLRP1 promoted mitochondrial fusion, and further suppressed tumor growth and enhanced cisplatin sensitivity, which was mediated by inhibition of NF-κB." (PMID 39258674, 2024). "Four potential antigens associated with tumor pyroptosis (CARD8, NAIP, NLRP1, and NLRP3) were screened as candidate molecules for future mRNA vaccine development." (PMID 38166691, 2024). "Conversely, in tumour samples with low NLRP1 expression, there is a notable enrichment of signalling pathways, include E2F targets, G2/M checkpoint, MYC targets version 1, MYC targets version 2 and oxidative phosphorylation." (PMID 39318060, 2024). "Insight of NLRP1 expression is significantly different in most tumour immune subtypes, thus, we further evaluated the relationship between NLRP1 levels and pathways using GSEA." (PMID 39318060, 2024). "Four tumor pyroptosis-associated antigens, CARD8, NAIP, NLRP1, and NLRP3, were screened as potential candidates for LUAD mRNA vaccine development." (PMID 38166691, 2024). "In especial, CASP4 can promote tumor progression by promoting the synthesis and accumulation of fatty acids, while NLRP1 acts on RAS/ERK signaling pathway." (PMID 35633405, 2022). "We further investigated the potential mechanisms through which NLRP1/NLRP3 were involved in tumor immune-regulation by analyzing the correlations between NLRP1/NLRP3 and immune cell marker genes." (PMID 36541912, 2022). "Analysis of immune infiltrates in TIMER showed that NLRP1/NLRP3 expression levels were significantly negatively correlated with tumor purity and positively correlated with multiple infiltrating immune cells in STAD." (PMID 36541912, 2022). "Conversely, we found that NLRP1 was downregulated in PAAD tumor samples and acted as an unfavorable biomarker of prognosis." (PMID 35000541, 2022). "Overall, high NLRP1/NLRP3 expression levels had a more significant correlation with higher tumor grade, cancer stage and more axillary lymph nodes metastases." (PMID 36541912, 2022). "Tumor tissues showed obviously higher expression levels of NLRP1, IL18, TNF, and CASP4 than did the normal tissues." (PMID 35785176, 2022).